LOXL3 (lysyl oxidase like 3)
Diseases named in the same sentence as LOXL3 in open-access papers (continued):
Sharing a sentence is not in itself a finding about the gene and the disease.
keratoconus (1 paper, 2019). A degenerative, structural disorder of the eye, characterized by a cone-shaped protrusion of the cornea. "In keratoconus, a disease characterized by irregular astigmatism resulting in significant visual impairment, LOXL3 expression is downregulated, as well as LOXL2 and LOXL4 expression, suggesting that LOX members may be involved in keratoconus pathogenesis." (PMID 31340433, 2019).
liver neoplasm (1 paper, 2022). Tumors or cancers of the LIVER. "As LOX and LOXL3 were both found to be overexpressed in LC and associated with worse OS, further exploration of potential interacting drugs was conducted by using Coremine Medical, which identified 30 drugs that were associated with both LOX and LOXL3 in liver neoplasms." (PMID 35311155, 2022).
lung carcinoma (1 paper, 2025). "CEBPA can recruit Tip60, thereby enhancing the transcription of LOXL2 and LOXL3 and the histone acetylation process in lung cancer cells." (PMID 41250755, 2025). "In summary, LOXL2 and LOXL3 are highly expressed in lung cancer and influence tumor prognosis by modulating immune infiltration." (PMID 41250755, 2025). "Knockdown of LOXL2/LOXL3 can inhibit EMT, cell proliferation, migration, and invasion processes, while also enhancing the apoptosis of lung cancer cells." (PMID 41250755, 2025). "In lung cancer, CEBPA enhances the transcriptional expression of LOXL2/LOXL3 and stabilizes BCL-2, thereby promoting the initiation and progression of lung cancer." (PMID 41250755, 2025). "Knockdown of LOXL2/LOXL3 inhibits EMT, proliferation, migration, and invasion, while promoting apoptosis in lung cancer cells." (PMID 41250755, 2025). "When the expression of LOXL3 is downregulated, the ubiquitination level of BCL-2 in lung cancer cells increases, while its expression level decreases." (PMID 41250755, 2025). "Finally, CEBPA binds to Tip60 to promote the transcription of LOXL2 and LOXL3, thereby enhancing the stability of BCL-2 and ultimately promoting the development and metastasis of lung cancer cells." (PMID 41250755, 2025).
lymph node metastasis (1 paper, 2025). "Patients with high LOXL3 expression often present with increased lymph node metastasis and reduced survival rates." (PMID 41250755, 2025). "However, recent studies have revealed that LOXL3 is frequently overexpressed in multiple types of malignant tumors, and its expression level is closely correlated with advanced tumor stage, lymph node metastasis, and poor patient prognosis." (PMID 41250755, 2025).
metabolic syndrome (1 paper, 2019). A cluster of metabolic risk factors for CARDIOVASCULAR DISEASES and TYPE 2 DIABETES MELLITUS. "In a murine model of diet-induced metabolic syndrome (high-fat high-simple carbohydrate, HFHSC) no changes were observed in the cardiac expression of Lox and Loxl3; however, metabolic syndrome significantly upregulated Bmp1, which increased LOX processing and activity and CCL." (PMID 31766500, 2019).
osteosarcoma (1 paper, 2026). A usually aggressive malignant bone-forming mesenchymal neoplasm, predominantly affecting adolescents and young adults. "Gene Expression Omnibus (GEO) analysis indicated that lysyl oxidase-like proteins—particularly LOXL1, LOXL2, and LOXL3—are overexpressed in osteosarcoma tissues compared to adjacent normal bone." (PMID 41399365, 2026). "Analysis of the GEO database revealed that LOXL1, LOXL2, and LOXL3 expression levels were significantly elevated in osteosarcoma tissue samples compared to normal bone, indicating their involvement in disease progression." (PMID 41399365, 2026). "In vitro experiments confirmed that treatment of osteosarcoma cells with FGF-23 increased LOXL2 mRNA and protein expression in a dose-dependent manner, while the effects on LOXL1 and LOXL3 were comparatively limited." (PMID 41399365, 2026).
periodontal diseases (1 paper, 2022). "Our study showed that LOXL3 could be a crucial factor in the early diagnosis of histopathological changes in periodontal diseases of T2DM patients." (PMID 36134856, 2022). "The significant upregulation of LOXL3 expression in the PDL of diabetic rats shows that LOXL3 may be a key factor in the occurrence and development of periodontal diseases in T2DM patients." (PMID 36134856, 2022).
Pulmonary hypoplasia (1 paper, 2016). "In the current study, the most remarkable phenotype of the LOXL3-deficient mice was pulmonary hypoplasia at the end of the embryonic period." (PMID 27645581, 2016). "Thus, we suggested that the increased accumulation of elastic fibres in the LOXL3-deficient lungs may be one of the factors causing pulmonary hypoplasia." (PMID 27645581, 2016).
serous ovarian carcinoma (1 paper, 2020). "The results indicated that the overexpression of LOX, LOXL1, LOXL2, LOXL3, and LOXL4 mRNA in serous ovarian carcinoma patients was related to unfavorable OS and PFS." (PMID 33058284, 2020).
systemic hypertension (1 paper, 2019). "In systemic hypertension, high LOXL3 expression was observed in cardiac fibroblasts and cardiomyocytes, leading to increased fibrillary collagen crosslinking, and cardiac ECM remodeling, which caused ventricular stiffness and cardiac diastolic dysfunction." (PMID 31340433, 2019).
tumor (32 papers, 2015 to 2025). "Intriguingly, the incidences of gene mutations, amplifications, and deep deletions associated with LOXL3 exhibit marked variability across diverse cancer subtypes, highlighting the gene’s distinct mutational landscapes in different tumor contexts." (PMID 41250755, 2025). "The restored expression of S704D-LOXL3 in AK2-deficient cells efficiently rescued the resistance of tumor cells to chemotherapy, further validating that LOXL3 acts downstream of AK2." (PMID 37253718, 2023). "High mRNA levels of LOX and LOXL2 were associated with advanced PDAC stage, while elevated LOX and LOXL3 expression correlated with high tumor grade." (PMID 35433829, 2022). "All genes encoding the LOX family, except Loxl3, had significantly higher mRNA expression in the tumour tissue in vivo than in the tumour cells in vitro." (PMID 26804196, 2016). "Furthermore, comprehensive analysis of TCGA tumor samples reveals that the R375C substitution is the most prevalent point mutation in LOXL3." (PMID 41250755, 2025). "Furthermore, a close association between the expression of LOX and LOXL3 with tumor immune infiltration was verified, uncovering the potential molecular mechanism underlying the carcinogenesis in PDAC." (PMID 35433829, 2022). "Previous studies investigating the role of LOXL3 in cancer have found an association with tumor progression and metastasis through physical interaction with SNAIL, a transcription factor involved in the epithelial–mesenchymal transition process and cell proliferation." (PMID 34360836, 2021). "This article reviews the specific roles and potential molecular mechanisms of LOXL3 in cancer, covering its associations with key cancer pathological processes such as epithelial-mesenchymal transition, maintenance of genomic stability, and regulation of the tumor microenvironment." (PMID 41250755, 2025). "Interestingly, we found that LOXL3 hypomethylation status is associated with LOXL3 upregulation in melanoma tumor samples and cell lines, supporting epigenetic regulation as one mechanism contributing to maintain high LOXL3 expression in this tumor type." (PMID 29229995, 2018). "It is also important to thoroughly examine the subcellular location of the LOXL3-sv1 and LOXL3-sv2 proteins in malignant tumors as well as the mechanism by which they contribute to tumor development." (PMID 41250755, 2025). "A study indicates that the expression of LOXL3, like other members of this protein family, was correlated with tumor invasion, lymph node metastasis, and poorer prognosis of patients." (PMID 40906383, 2025). "An in-depth analysis of the mechanisms by which LOXL3 operates across different tumors will not only offer novel insights into tumor heterogeneity, but also provide a theoretical foundation for developing precision therapeutic strategies targeting LOXL3." (PMID 41250755, 2025). "Studies indicate that elevated LOXL3 expression is positively correlated with increased tumor thickness and mitotic activity." (PMID 41250755, 2025). "As a prognostic marker reflecting the degree of tumor differentiation, LOXL3 is a major target of YTH domain family protein 3 (YTHDF3)." (PMID 41250755, 2025). "This indicated a decrease in fibrils in ADAM10 KO tumours, reflecting the reduced levels of collagens, the cross-linker LOXL3, and other ECM proteins identified above." (PMID 41226720, 2025). "Understanding the function of the LOXL3 gene in tumor formation and progression requires both substantial in vivo research and the use of engineered rodent models, such as knockout mice." (PMID 41250755, 2025). "It focuses on clarifying the specific molecular pathways through which LOXL3 promotes pro-tumor activities in different tumors, as well as the regulatory effects of these pro-tumor activities on patients’ relevant prognosis." (PMID 41250755, 2025).
tumor (continued). "Aminopropionitrile has a strong effect in the treatment of HCC and can be used as a potential therapeutic drug targeting LOXL3-related pathways, providing a new intervention direction for improving chemoresistance and inhibiting tumor progression in HCC." (PMID 41250755, 2025). "Mechanistic investigations reveal LOXL3’s capacity to remodel the tumor immune microenvironment through dual modulation of immune cell recruitment and cytokine network dynamics." (PMID 41250755, 2025). "Collectively, this regulatory mechanism establishes a direct functional link between LOXL3 and the processes of tumor progression and metastasis." (PMID 41250755, 2025). "Combining oxaliplatin with inhibitors targeting the LOXL3-DHODH axis effectively suppressed tumor growth in mouse models with advanced HCC with the LOXL3-S704D mutant, highlighting a novel resistance mechanism and therapeutic strategy." (PMID 38997696, 2024). "In IDC- NST, LOXL3 is expressed and enriched in focal areas at the invasive front by tumor cells that are in direct contact with the stroma." (PMID 35292774, 2022). "Further analysis suggested that LOX and LOXL3 strongly correlated with tumor-infiltrating lymphocytes (TILs), various immune signatures, and immune checkpoints." (PMID 35433829, 2022). "The expression of LOXL3 was detected mainly in the nucleus, and the expression of LOXL3 was correlated with tumor invasion, lymph node metastasis, and poorer prognosis of patients." (PMID 35126449, 2021). "We noted a significant morphological change of U87MG cells after LOXL3 downregulation, with enlargement of the tumor cell surface." (PMID 34360836, 2021). "We found that the mRNA expression of all members of the LOX family—except Loxl3—were up-regulated both in the tumour tissue and in the normal prostate tissue adjacent to the tumour." (PMID 26804196, 2016). "Moreover, the IL-11-overexpressing subclone facilitated increased tumor growth in the presence of LOXL3, indicating that LOXL3-overexpressing cells benefited from the IL-11-overexpressing cells." (PMID 39774289, 2025). "Knockdown of LOXL3 reduces tumor cell proliferation and decreases lymph node metastasis." (PMID 41250755, 2025). "This could explain the stochastic occurrence of invasive strands at the tumor/organoid ECM interface where the ECM becomes stiffer because of remodeling including Loxl3-mediated crosslinking." (PMID 38849373, 2024). "Although we observe LOXL3 expression prominently in approximately half of the whole slide sections analyzed, these LOXL3 enriched focal regions can be easily missed when analyzing 3 mm tumor cores on a TMA." (PMID 35292774, 2022). "The processes involved with LOXL3 may have a close relationship with tumour invasion and metastasis." (PMID 36324258, 2022). "In terms of tumours, some reports have pointed out that LOXL3 could affect the migration and invasion of tumour cells, and downregulation of LOXL3 could inhibit the ability of migration and invasion in tumour cells." (PMID 36324258, 2022). "Because these functions are most likely catalytic independent, it may suggest that Loxl2 plays a more diverse role in tumor biology than Loxl3." (PMID 35292774, 2022). "In recent years, people gradually discovered the essential role of LOXL3 in tumor progression." (PMID 36293126, 2022). "Accordingly, primary tumors developed in the flanks of syngeneic mice showed a delayed growth upon inoculation of Loxl3-silenced B16-F10 cells compared to those derived from control cells, accompanied by a reduction in tumor incidence and an increase in tumor latency." (PMID 35267510, 2022). "Overexpression of LOXL2 or LOXL3 in epithelial cells causes EMT, indicating that they may play a role in tumor growth." (PMID 36314741, 2022). "Moreover, a morphological change was observed after LOXL3 silencing characterized by an enlargement of the tumor cell surface, which was more prominent with siRNA1." (PMID 34360836, 2021).
tumor (continued). "Invasiveness is a major determinant of the recurrence and poor outcome of GBM patients, and downregulation of LOXL3 may contribute to halting the tumor cell invasion." (PMID 34360836, 2021). "Furthermore, LOXL3 expression has been detected in circulating tumor cells of colorectal cancer, and its expression has been correlated with treatment response and prognosis." (PMID 31340433, 2019). "Besides, tumorigenic A375P cells depleted for LOXL3 showed increased latency and delayed tumor growth compared to control cells." (PMID 29229995, 2018). "LOXL3 may regulate the secretion of cytokines and chemokines by tumor cells, recruit immunosuppressive cells into the tumor microenvironment, and inhibit the body’s anti-tumor immune response, thereby affecting tumor prognosis." (PMID 41250755, 2025). "Similarly, in invasive ductal breast cancer of no special type (IDC-NST), LOXL3 induces cross-linked bundling of collagen (increased thickness and network pore size) and promotes the collective invasion of frontier tumor cells." (PMID 36293126, 2022). "Hence, lowering LOXL3 expression may increase tumor resectability and decrease the rate of tumor recurrence, thereby improving the outcomes of patients with GBM." (PMID 34360836, 2021). "The results demonstrated a significant decrease in the expression of Ki67 protein in tumor tissues from sh-LOX, sh-LOXL1, sh-LOXL2, sh-LOXL3, and sh-LOXL4 mice, compared to the sh-NC group." (PMID 40270974, 2025). "RT-qPCR and WB techniques were used to detect the expression of LOX, LOXL1, LOXL2, LOXL3, and LOXL4 in tumor tissues." (PMID 40270974, 2025). "Flow cytometry analysis revealed a significant reduction in the proportion of M2 macrophages in the tumor tissues of sh-LOX, sh-LOXL1, sh-LOXL2, sh-LOXL3, and sh-LOXL4 groups of mice compared to the sh-NC group." (PMID 40270974, 2025). "Immunofluorescent staining revealed increased infiltration and exhaustion of CD8+ T cells in the tumor tissues of mice in the sh-LOX, sh-LOXL1, sh-LOXL2, sh-LOXL3, and sh-LOXL4 groups, compared to the sh-NC group." (PMID 40270974, 2025). "Preliminary observations indicate a decrease in the tumor volume and weight of mice in the sh-LOX, sh-LOXL1, sh-LOXL2, sh-LOXL3, and sh-LOXL4 groups compared to the sh-NC group." (PMID 40270974, 2025). "The results indicated a significant increase in the expression of INF-γ and TNF-α in the tumor tissues of mice from the sh-LOX, sh-LOXL1, sh-LOXL2, sh-LOXL3, and sh-LOXL4 groups compared to the sh-NC group." (PMID 40270974, 2025). "In tumors, LOXL3 interacts with SNAIL, a transcription factor involved in the epithelial–mesenchymal transition process, thereby contributing to metastasis and tumor progression." (PMID 34360836, 2021). "Collectively, these results suggest that LOXL3 is overexpressed in GBM, impacting overall survival and playing a still unexplored role in this tumor type." (PMID 34360836, 2021). "Collectively, the upregulated genes after LOXL3 silencing corroborate the observed U87MG phenotype alteration with cell spreading, increased cellular adhesion, and decreased tumor cell invasion." (PMID 34360836, 2021). "LOXL3 interaction with SNAIL in the perinuclear envelope cooperates to downregulate CDH1 expression, thus suggesting LOXL3 involvement in tumor progression and metastasis." (PMID 31340433, 2019). "In the absence of the tumor microenvironment, Zeb1/2 levels were unaffected by Loxl3 silencing in MeL3 cells, although both gene and protein levels of Snail1 and Prrx1 EMT-TFs were markedly downregulated." (PMID 35267510, 2022). "However, there is more and more evidence indicating that lysyl oxidases also promote tumor cells metastasis by targeting intracellular proteins, such as histones or transcription factors, such as snail, in the cases of LOXL2 and LOXL3." (PMID 35682926, 2022). "Meanwhile, tumor grade was significantly correlated with the expression of LOX and LOXL3." (PMID 35433829, 2022).
tumor (continued). "Knockdown of LOXL3 can upregulate the expression of proliferation-related genes, such as cell cycle protein D1 (CCND1), in a STAT3-dependent manner, thus the overexpression of LOXL3 in HCC cells can significantly delay the cell cycle and inhibit the growth of tumor cells." (PMID 36293126, 2022). "Although LOXL3 plays different roles in tumorigenesis and in tumor progression, there are no studies investigating the expression of LOXL3 expression in GBM." (PMID 34360836, 2021). "The aim of this study was to prospectively validate a gene expression panel (composed of GAPDH, VIL1, CLU, TIMP1, TLN1, LOXL3 and ZEB2) for detecting circulating tumor cells (CTCs) as prognostic and predictive tool in blood samples from 94 metastatic CRC (mCRC) patients." (PMID 28608814, 2017). "While LOXL3-overexpressing cells expanded rapidly, they did not drive tumor growth." (PMID 39774289, 2025). "Based on the literature, LOXL3, CHD7 and PDE3A could regulate the malignant behaviour of tumours." (PMID 36324258, 2022). "We detect LOXL3 expression in 5 out of the 12 IDC-NST samples tested, but do not observe correlations between tumor grade or mitotic index in these samples (data not shown)." (PMID 35292774, 2022).